INS (insulin)
Diseases named in the same sentence as INS in open-access papers (continued):
Sharing a sentence is not in itself a finding about the gene and the disease.
diabetes (continued). "Insulin dose (U/kg/day) was lower in obese individuals compared to normal BMI, with mean (95 % CI) 0.72 (0.62–0.83) vs. 0.88 (0.84–0.92) U/kg/day for diabetes duration <5 years and 0.84 (0.77–0.92) vs. 0.99 (0.97–1.01) U/kg/day for duration ≥5 years." (PMID 27011769, 2016). "For diabetes patients with cancer, the development of insulin resistance is reported to be combined with frequent insulin receptor overexpression and increased insulin activity in cancer cells." (PMID 26939025, 2016). "At 8 weeks, the clinical impression of evolution to a transient diabetes (decreasing needs of insulin with very satisfactory weight gain) was genetically confirmed (paternal uniparental disomy of chromosome 6)." (PMID 27909691, 2016). "This APC function of insulin-specific B cells is likely their mechanism of action in driving diabetes." (PMID 27834793, 2016). "Metformin, when used in treating diabetes with other anti-diabetic drugs, acts by optimising the effect of endogenous insulin." (PMID 26821281, 2016). "In conclusion, our data indicate that there is significantly less IFG, lower insulin levels, and insulin resistance, but higher diabetes prevalence in Fukuoka men than in Framingham men, indicating that insulin deficiency may be an important cause of diabetes in Japan." (PMID 27830830, 2016). "As an example, diabetic patients receiving insulin are a subgroup with very specific characteristics; they usually have more severe forms of diabetes and greater prevalence of comorbidities that can lead to an increased risk of cancer." (PMID 25916213, 2016). "Diabetes mellitus is the most common metabolic disorder characterized by hyperglycemia that results from defects in insulin secretion or action or both, which affect carbohydrate, lipid, protein, and nucleic acid metabolism." (PMID 27579151, 2016). "Average duration of diabetes was 12.8 years (±9.1), and 31.8% of participants were on insulin therapy." (PMID 28076599, 2016). "When used properly, glucose meters for self-measurement of blood glucose allow diabetes patients to determine their blood glucose level and can guide insulin dose adjustment." (PMID 27625706, 2016). "Mice also developed diabetes with increases in plasma glucose, insulin, hepatic triglyceride levels, and changes in the plasma lipid and adipokine levels." (PMID 26891322, 2016). "Safe and effective insulin therapy for diabetes mellitus requires initial dose titration and regular adjustments based on blood glucose (BG) monitoring." (PMID 27145817, 2016). "Hyperglycemia is a characteristic of diabetes mellitus, a metabolic disease due to impaired insulin secretion (type I diabetes), insulin action (type II diabetes), or both." (PMID 27338453, 2016). "The blood glucose lowering effect of Z. chalybeum was compared with that of metformin, a standard drug which has been in use for many years for treatment of diabetes and acts by stimulating insulin secretion from pancreatic β-cells." (PMID 27069932, 2016). "In case of starvation or diabetes mellitus, the levels of ketone bodies are significantly increased due to high levels of fatty acids and low insulin." (PMID 27821850, 2016). "The dog with the most robust anti-insulin T-cell response (MD 02) also had detectable anti-insulin antibodies (0.234 nU/mL), and its diabetes was poorly controlled on NPH insulin." (PMID 27031512, 2016). "This review describes the most reliable sources of stem cells that have been developed to produce insulin and their most relevant experimental applications for the cure of diabetes." (PMID 27400873, 2016). "Akita mice carry a toxic-gain-of- function Ins2 gene mutation encoding proinsulin-C(A7)Y, similar to that described in human Mutant Ins-gene induced Diabetes of Youth, which decreases intra-islet insulin." (PMID 28702245, 2016). "Because GIP and GLP-1 are rapidly inactivated by DPP4, DPP4 inhibitors are widely used for clinical treatment of diabetes as an insulin secretagogue." (PMID 27053237, 2016).
diabetes (continued). "After 20 years of diabetes, almost all type-1 diabetes patients, 80% of insulin-dependent diabetics, and 50% of insulin-independent type-2 diabetic patients will develop retinopathy." (PMID 27313624, 2016). "Rats treated with Tac exhibited symptoms of diabetes mellitus, as demonstrated by increased area under the curve of glucose (AUCg) values and lower levels of serum insulin as compared with those in rats treated with vehicle (VH)." (PMID 27436514, 2016). "Insulin deficit during diabetes, thus results in the accumulation of dietary lipids leading to abnormalities such as hyperlipidaemia raising the risks factors for coronary heart disorders." (PMID 27003006, 2016). "Resveratrol is a natural polyphenol that has been proposed to improve glycemic control in diabetes, by mechanisms that involve improvement in insulin secretion and activity." (PMID 27366200, 2016). "After adjusting for age, gender, ethnicity, diabetes duration, HbA1c, BMI, insulin treatment, number of anti-hypertensives, history of PVD, and baseline eGFR (R2 0.87), baseline foot insensitivity was associated with study-end eGFR (B = −3.551, p = 0.036)." (PMID 27876022, 2016). "The formulation has potential to be developed into a self-regulated insulin delivery system for the treatment of diabetes." (PMID 27740594, 2016). "The infirmity of insulin secretion and insulin action on glucose uptake in muscles leads to type-2 diabetes mellitus." (PMID 27304951, 2016). "More than 40 % of our patients were treated with insulin alone which is distinctly higher as in general diabetes cohorts including German cohorts in which only 10–20 % are treated with insulin monotherapy." (PMID 27286816, 2016). "Beneficial effects in metabolic parameters were achieved, including improvement in glucose-insulin homeostasis, insulin resistance, and lipid homeostasis during reduction of anti-diabetes treatment." (PMID 27664051, 2016). "Among the 82 patients, insulin treatment was started in only six (7.3%) patients at more than 10 years after the diabetes onset." (PMID 27177031, 2016). "Our results indicate that hPSC-derived ECCs can effectively secrete insulin for the treatment of diabetes." (PMID 27731367, 2016). "The DFU group also had a longer diabetes duration, more insulin use, lower eGFR and higher MNSI neuropathy scores than the DMC group (all p < 0.05)." (PMID 27629263, 2016). "Supplementation of 0.12% myricetin in mice fed a high-fat high-sugar diet resulted in decreased body weight and improved hypercholesterolemia and hypertriglyceridemia, confirming that myricetin can improve insulin secretion and reduce diabetes and obesity." (PMID 27092490, 2016). "Maintenance of normal glucose tolerance in the face of insulin resistance is dependent on the compensatory increase in circulating insulin levels to overcome insulin resistance; when this compensation is insufficient, diabetes develops." (PMID 27846285, 2016). "Age, body mass index, hypertension, diabetes, systolic blood pressure, insulin resistance, fasting glucose and high-sensitivity C-reactive protein levels were increased with the increment of UACR (P for trend <0.05)." (PMID 28000719, 2016). "Diabetes mellitus is a group of metabolic diseases characterized by elevated blood glucose levels resulting from defects in insulin secretion, insulin action, or both." (PMID 27069932, 2016). "Relevant to diabetes is the fact that high glucose levels increase the GlcNAcylation of proteins within the insulin signaling pathway which contributes to insulin resistance." (PMID 26960196, 2016). "The significant reduction of at list one of the primary outcome endpoints which include levels of fasting plasma glucose, postprandial blood glucose, HbA1c, insulin, insulin resistance and onset of diabetes were demonstrated in all studies." (PMID 26900391, 2016).
diabetes (continued). "Insulin is probably the most important tool used in diabetes care to control hyperglycemia and thereby to a large degree reduce the risk of late complications like DN." (PMID 27757071, 2016). "The treatment of diabetes in the future should exert more efforts on improving insulin resistance and maintaining normal insulin secretion." (PMID 27656237, 2016). "We calculated the optimal cut-off value of GADAb levels for the progression to insulin-requiring diabetes by conducting a ROC curve analysis of the NIR-SPIDDM and IR-SPIDDM groups." (PMID 27177031, 2016). "The data indicate that diabetic STZ-rats are suitable to address diabetes-induced renal dysfunction and that these rats respond to exogenous insulin when analyzing glucose levels as well as kidney parameters." (PMID 27253523, 2016). "In any case, impaired insulin sensitivity is a reasonable explanation for the increased incidence of impaired glucose tolerance and onset diabetes observed in women with PCOS." (PMID 27505055, 2016). "Among the participants, 59.4% used insulin as the most commonly used medication for diabetes treatment; 67.9% of the individuals had other chronic diseases, and 64.7% had complications of diabetes." (PMID 27994961, 2016). "Reimbursed diabetes education was initially introduced in Belgium in 1988 in a hospital ambulatory setting for people with advanced diabetes, i.e. those in need of three or more insulin injections per day." (PMID 27727281, 2016). "Among all contributing factors for diabetes, compromised insulin sensitivity is perhaps most crucial leading to the consequence of an overstimulation of pancreatic secretion of insulin and dampened glucose and fatty acid metabolism." (PMID 27634872, 2016). "The presence of diabetes correlated negatively with insulin clearance in the overall multivariate model." (PMID 27846285, 2016). "Our innovative study, the Telemedicine for Gestational Diabetes Mellitus (TeleGDM) trial, uses a Web-based approach to augment the management of women with insulin-treated GDM." (PMID 27507708, 2016). "The items in both the general diabetes subscale and the insulin-use subscale were considered relevant and appropriate." (PMID 27366112, 2016). "The significant role of insulin in the analyzed network implies definition of a crucial role for insulin as like as its role in the diabetes." (PMID 28224024, 2016). "Here, the authors identify Aldh3 as a marker of de-differentiating β-cell in animal models of diabetes, and show Aldh3+ cells have impaired insulin secretion and mitochondrial dysfunction." (PMID 27572106, 2016). "This and other studies demonstrated clearly that intensive therapy with insulin, leading to normoglycemia in rats with diabetes, does prevent the delay in wound healing of ocular surface epithelium observed in poorly controlled diabetic animals." (PMID 27703986, 2016). "For the patients accompanied with diabetes mellitus or renal transplantation, insulin therapy with a strict surveillance of glycemia or the therapy with improvement of renal function was prescribed." (PMID 26758904, 2016). "Compared with other oral medications of diabetes and insulin therapy, α-glucosidase inhibitors have the most notable characteristics of being able to effectively treat or prevent high blood glucose from diabetic or prediabetic patients." (PMID 27088095, 2016). "Some authors have also considered pharmacological treatments for DM, such as insulin, as a risk factor for the presence of DPN (OR 1.57 [95% CI 1.15–2.13]), and related with greater risk of numbness (OR 3.21 [95% CI 1.52–6.97]), after adjustment for duration of diabetes, HbA1c levels, and age." (PMID 28058263, 2016). "HbA1c levels were numerically higher in regions outside Europe and Canada (Latin America, Middle East, Russia and SE Asia groups), whereas the duration of diabetes and of insulin use were numerically higher in Northern Europe/Canada." (PMID 27161418, 2016).
diabetes (continued). "Generation of functional pancreatic insulin-producing beta cells for the effective treatment of diabetes is a key area of translational research." (PMID 26733021, 2016). "A numerical increase in hypoglycaemia rate was observed with increased duration of diabetes and increased duration of insulin therapy for both T1D and T2D." (PMID 27161418, 2016). "Diabetes has become a worldwide health problem in our society and curative therapies to restore the insulin producing beta cells are urgently needed." (PMID 27374092, 2016). "The generation of insulin-producing β cells from stem cells in vitro provides a promising source of cells for cell transplantation therapy in diabetes." (PMID 26759123, 2016). "Patients were insulin dependent, had undetectable stimulated C-peptide, history of highly problematic diabetes control, hypoglycemia unawareness, and severe metabolic lability." (PMID 27285580, 2016). "Type 2 diabetes mellitus (DM) arises from a defect in insulin usage by metabolic organs, such as muscle, liver, and adipose tissue." (PMID 27070585, 2016). "Diabetes mellitus, commonly referred to as diabetes, is characterized by hyperglycemia due to impaired insulin secretion and aberrant glucagon secretion." (PMID 27608006, 2016). "Transfer from insulin is successful for most KCNJ11 patients and is best predicted by the in vitro response of the specific mutation and the duration of diabetes." (PMID 27033559, 2016). "Type 2 diabetes mellitus is a complex metabolic disease and its pathogenesis involves abnormalities in both peripheral insulin action and insulin secretion." (PMID 27562101, 2016). "It is known that a single bout of exercise makes skeletal muscle more sensitive to insulin, while lifestyle modification through regular exercise reduces the incidence of diabetes by 60%." (PMID 28248217, 2016). "Nonetheless, using a Mendelian randomization approach, a recent study did not support a causal relationship between reduced circulating adiponectin levels and two obesity-related metabolic disorders, i.e., insulin sensitivity and type 2 diabetes mellitus." (PMID 27227680, 2016). "The majority of patients with diabetes were insulin-treated at enrollment: 66.7 % among the linezolid-treated and 77.1 % among the vancomycin-treated patients." (PMID 27600290, 2016). "The Japanese Society of Hypertension recommends the use of angiotensin-converting enzyme inhibitors (ACE inhibitors) and angiotensin receptor blockers (ARBs), which enhance insulin sensitivity, for patients with diabetes and hypertension." (PMID 27437997, 2016). "In patients with type 2 diabetes mellitus, a disease characterized by hyperglycemia due to insulin insensitivity or insufficient insulin secretion, the levels of IR and associated downstream signaling pathways are perturbed." (PMID 27384998, 2016). "Nevertheless, our study describes different patterns of relationships of premorbid intelligence vs. cognitive impairment to BMI, insulin and diabetes in the elderly." (PMID 27642517, 2016). "SGLT2 inhibitors are a new class of anti-diabetes treatment, with a novel and insulin- independent mechanism." (PMID 27611858, 2016). "In contrast, β-cells that initially produce insulin in sufficient quantities eventually produce insufficient quantities, thereby leading to the onset and progression of diabetes." (PMID 27721914, 2016). "Frequent spikes of post‐prandial glucose can affect insulin secretion and β‐cell dysfunction accelerating the onset of diabetes." (PMID 26887821, 2016). "Mice with β-cell-specific HDAC3 deletion displayed decreased insulin content, disrupted glucose-stimulated insulin secretion and tolerance, and dramatically enhanced susceptibility to low dose STZ induced diabetes." (PMID 27542279, 2016).
diabetes (continued). "Our formative research indicated that patients with poorly controlled diabetes faced significant financial barriers to insulin, a finding in line with global literature primarily viewing access to insulin as problem of affordability and availability." (PMID 27134081, 2016). "Due to their physiological relevance, we focus on determining changes induced by insulin and/or diabetes on activity and expression of CAT-1." (PMID 27014078, 2016). "Taken together, these findings demonstrate, for the first time, that miR-155 is a positive regulator of insulin sensitivity with potential applications for diabetes treatment." (PMID 27711113, 2016). "SQ Lispro insulin improves mean glucose concentration (MGC) in diabetes while minimizing postprandial hypoglycemia." (PMID 26819233, 2016). "Diabetes mellitus characterized by hyperglycemia as a result of insufficient production of or reduced sensitivity to insulin poses a growing threat to the health of people." (PMID 27535125, 2016). "Diabetes self-efficacy, blood glucose monitoring, and adherence to diabetes medication (insulin or oral medications) were reportedly high at baseline and remained so for approximately 6 months after the initial TREAT visit." (PMID 27869655, 2016). "As she participated in a lot of sport, many of her queries about her type 1 diabetes related to the impact of exercise on diabetes and insulin dosage." (PMID 27359321, 2016). "The current classes of hypoglycemic agents used for the treatment of diabetes include insulin secretagogue, liver gluconeogenesis inhibitor, insulin sensitizer, and α-glucosidase inhibitor." (PMID 27974904, 2016). "Blood samples were collected from indwelling vein catheters for measurements of glucose and the diabetes related hormones insulin, glucagon and active glucagon-like peptide-1." (PMID 26859145, 2016). "In LMICs, barriers to diabetes medication include the affordability and availability of essential diabetes medications comprising insulin, glibenclamide, and metformin." (PMID 27938647, 2016). "Previous research has shown that a higher level of serum CysC was related to decreased insulin sensitivity in 71 Caucasian patients with type 1 diabetes mellitus." (PMID 26849560, 2016). "The two major obstacles in the successful transplantation of islets for diabetes treatment are inadequate supply of insulin-producing tissue and immune rejection." (PMID 26756576, 2016). "During the development of the type 2 diabetes mellitus rat model, both the fasting serum levels of insulin and leptin (ng/ml) elevated significantly and the fasting plasma ghrelin concentration decreased the hypothalamic NPY (pg/mg) content significantly." (PMID 27867820, 2016). "Diabetes mellitus, a state of chronic hyper-glycemia, is characterized by increased insulin resistance of peripheral tissues (type 2 diabetes) or reduced pancreatic beta cell mass and absolute insulin storage (type 1 diabetes)." (PMID 26459400, 2016). "Diabetes mellitus (or diabetes) is a chronic, lifelong condition, in which impaired insulin secretion and variable degrees of peripheral insulin resistance lead to hyperglycemia and affect the body’s ability to use food energy." (PMID 27570525, 2016). "The UK Prospective Diabetes Study (UKPDS) reported that maintenance of tight glycemic control in T2DM with insulin treated led to a significant increase in the incidence of hypoglycemia." (PMID 27158818, 2016). "Before the discovery of insulin, medicinal plants were widely used for the treatment of diabetes in Iran." (PMID 27047810, 2016). "In our study, induction of diabetes with alloxan was associated with a marked reduction in liver glycogen stores which could be attributed to a decrease in the availability of the active form of enzyme glycogen synthetase probably because of low level of insulin." (PMID 27538464, 2016).